GPX3 (glutathione peroxidase 3)
Diseases named in the same sentence as GPX3 in open-access papers (continued):
Sharing a sentence is not in itself a finding about the gene and the disease.
cardiovascular disease (11 papers, 2012 to 2025). "Nevertheless, the precise mechanisms that underlie the role of GPx-3 in cardiovascular disease warrant further investigation." (PMID 41152890, 2025). "Loss of Gpx3 is related to the occurrence of cardiovascular diseases." (PMID 35997993, 2023). "Experimental studies have shown a role for a subset of redox-active selenoproteins, including GPx1, GPx3, GPx4, and Txnrd2, in protecting against complex cardiovascular diseases, in part, by attenuating the harmful effects of reactive oxygen species." (PMID 34579115, 2021). "The recent data from the Minnesota Heart Survey also indicate that selenium status in the form of GPX3 activity is inversely correlated to cardiovascular disease mortality even in a selenium replete population." (PMID 31404994, 2019). "GPx-3 is also associated with various nonneoplastic diseases such as cardiovascular diseases and metabolic syndrome." (PMID 41152890, 2025). "However, the detailed mechanisms of GPX3 in cardiovascular diseases remain to be fully elucidated." (PMID 38927092, 2024).
adenocarcinoma (4 papers, 2017 to 2024). A common cancer characterized by the presence of malignant glandular cells. "GPX3 inhibits prostate tumorigenesis in transgenic adenocarcinoma of the mouse prostate (TRAMP) mice." (PMID 27891827, 2017).
kidney disease (4 papers, 2011 to 2024). "CKD patients typically exhibit low GPX3 levels, closely associated with the development of kidney disease-induced cardiac complications." (PMID 38927092, 2024). "Based on the known functions of the DKD candidate marker genes, it appears that many associate with kidney diseases, and our stress score genes, particularly GPX3, HRSP12, MSRA, MSRB1, and CRYAB, protect the cell and/or cellular proteins during stress." (PMID 37216114, 2023). "Thus, GPx3 deficiency was found to be a significant contributor to the development of kidney disease-induced cardiac disease." (PMID 32823917, 2020). "Several authors have shown a gradual decrease in the GPx3 activity along with the progression of the kidney disease." (PMID 32823917, 2020).
bone and joint diseases (2 papers, 2023 to 2024). "Furthermore, methylation in the promoter region of GPX3 and downregulation of GPX3 have been observed in patients with Kashin–Beck disease, an endemic osteoarthropathy." (PMID 37021050, 2023).
cardiac disease (2 papers, 2020). "Studies have shown that reduced GPx3 expression is associated with liver and heart disease in humans." (PMID 33322741, 2020). "GPx3 downregulation enhances liver aging, and an inadequate GPx3 level is a significant factor in human heart disease." (PMID 33322741, 2020). "Furthermore, reduced GPx3 expression is a contributing factor to circulatory diseases, and a contributing factor to developing kidney-induced cardiac disease." (PMID 32210049, 2020).
brain disease (1 paper, 2012). "GPX3 is known as plasma glutathione peroxidase and has not been investigated in the context of brain disease and injury." (PMID 22701605, 2012).
psychiatric disorder (1 paper, 2022). A disorder characterized by behavioral and/or psychological abnormalities, often accompanied by physical symptoms. "Moreover, a recent study found elevated GPX3 enzyme levels in cerebrospinal fluid among participants with psychiatric disorders (n = 98, including 27 with BD) compared with controls." (PMID 34387669, 2022). "This SNP has not been previously linked to any other psychiatric disorders, but a previous study has suggested a protective effect of GPX3 during brain maturation and aging." (PMID 34387669, 2022).
GPX3 also shares sentences with these, for which no sentence is quoted: esophageal cancer (5 papers); amyotrophic lateral sclerosis (3); Arterial thrombosis (3); prostatic intraepithelial neoplasia (3); acute coronary syndrome (2); acute respiratory distress syndrome (2); ANCA-associated vasculitis (2); Ascites (2); colorectal tumor (2); cyst (2); head and neck squamous cell carcinoma (2); immune disorders (2); interstitial lung disease (2); invasive breast carcinoma (2); prostate (2); rectal cancer (2); viral infection (2); AIDS (1); Barrett adenocarcinoma (1); cardiomyopathy (1); cervical squamous cell carcinoma (1); chronic beryllium disease (1); chronic myeloid leukemia (1); clear cell ovarian cancer (1); dementia (1); depression (1); encephalitis (1); endotoxemia (1); fibrosarcoma (1); gallbladder cancer (1).
A further 51 diseases each share a sentence with GPX3 in 1 paper.